RNU6-48P (RNA, U6 small nuclear 48, pseudogene)
Synonyms: RNU6-48
Gene: Small nuclear RNA gene on chromosome 1 (27,325,219 to 27,325,325, forward strand). Ensembl gene ENSG00000206888.
Homologues: Orthologues: chimpanzee U6 (97% identical), guinea pig U6 (92% identical), guinea pig U6 (86% identical). Paralogues in human: RNU6-25P (97% identical), RNU6-33P (97% identical), RNU6-1 (96% identical), RNU6-2 (96% identical), RNU6-27P (96% identical), RNU6-3P (96% identical), RNU6-4P (96% identical), RNU6-5P (96% identical), RNU6-6P (96% identical), RNU6-9 (96% identical), RNU6-12P (95% identical), RNU6-13P (95% identical), and 1287 more.